GLS (glutaminase)
Diseases named in the same sentence as GLS in open-access papers (continued):
Sharing a sentence is not in itself a finding about the gene and the disease.
tumor (continued). "qRT-PCR analysis further revealed that mitochondrial glutaminase 1 (GLS1), involved in tumor growth 44, and phosphoenolpyruvate carboxykinase (PCK2), which regulates tumor-initiating cells 45, were substantially downregulated by the depletion of KDM4B." (PMID 34335964, 2021). "Recent studies have found that antisense lncRNA of glutaminase (GLS-AS) is involved in the pathogenesis of pancreatic cancer by mediating the mutual feedback of Myc and GLS in the tumor nutrients stress microenvironment." (PMID 33849550, 2021). "Renal glutaminase (GLS1) provides the antioxidants glutathione (GSH) and nicotinamide adenine dinucleotide phosphate (NADPH) for tumor cell metabolism, and promotes tumor cell growth by reducing reactive oxygen species (ROS)." (PMID 34790132, 2021). "GLN uptake promoted both GLS and GLS2 mRNA expression after 6 h of stimulation, which promoted the use of GLN by tumor cells while stimulating downstream mTOR signaling to promote tumor progression." (PMID 34503536, 2021). "The deamination of glutamine by glutaminase (GLS) within the mitochondria yields glutamate and ammonia and, importantly, marks the first step of glutaminolysis, which contributes to tumor growth by promoting cell proliferation and repressing cell death." (PMID 34906193, 2021). "GLS inhibitors including BPTES (bis-2-(5-phenylacetamido-1,3,4-thiadiazol-2-yl)ethyl sulfide) and CB-839 have also been demonstrated to suppress tumor growth in liver and breast cancer mouse models." (PMID 33514004, 2021). "RT-qPCR analysis of GLS and MYC expression showed that both these genes are significantly upregulated in the metastatic tumor cells compared to the cells that originated from the primary tumor site." (PMID 34335968, 2021). "Ionizing radiation increased the protein expressions of ASCT2, GLS, and GLUD in order to upregulate the glutamine metabolic flux in tumor cells." (PMID 35028001, 2021). "In a previous study on matching control brain and tumor samples from GBM patients, it was further shown that tumors express elevated GLS protein levels." (PMID 32337072, 2020). "Combined treatment with the glutaminase inhibitor CB-839 and the PI3K/aldolase inhibitor NVP-BKM120 more consistently reduces cell growth of tumor xenografts." (PMID 33005401, 2020). "Pharmacological inhibition of GLS was also shown to be effective in eradicating the GBM stem-like cell population, which is thought to be responsible for therapy resistance and tumour recurrence." (PMID 33092283, 2020). "The example of striking discrepancies in anticancer efficacy of glutaminase inhibitor CB839 observed in vitro and in vivo highlights the crucial importance of tumor cell environment." (PMID 31319822, 2019). "Glutaminase 1 (GLS1), a key mitochondrial enzyme that controls glutamine metabolism and contributes to de novo GSH synthesis, is very important for tumor proliferation and survival." (PMID 31357507, 2019). "Direct perfusion with stable isotope-labeled glutamine into mouse tumor and measurement of glutamine derived aspartate as well as tumor glutamine uptake suggested glutaminolysis mechanisms compensating for suppressed glycolysis, which in turn could be restricted using an inhibitor of glutaminase." (PMID 30893889, 2019). "To correlate these findings with the GLS knockdown data in our xenograft model SUM-159PT, we analyzed these tumor lysates for both ATF4 levels and phospho-P70 S6K." (PMID 28950000, 2017). "We found that low-dose PTX down-regulated glutaminolysis-related genes (GLS, SLC7A11 and SLC1A5) and increased lactate production, resulting in decreased pH of the tumor microenvironment which inhibited tumor cell growth." (PMID 28522974, 2017). "Possibly offering the most important contribution to a major metabolic switch in tumor tissue, MYC strongly influences glutamine metabolism (Key factor 3) by regulating glutaminase (GLS) expression through miRNAs." (PMID 27590516, 2016).
tumor (continued). "In one study, when the MCF-7 cell line was co-cultured with fibroblasts, the expression of GLS, GDH, and SLC6A14 (glutamine importer) in tumor cells increased and glutamine neosynthesis decreased compared to when the cell line was cultured alone." (PMID 27447554, 2016). "Recent flux studies in tumor cells bearing isocitrate dehydrogenase 1 (IDH1) mutations indicate that these cells may be particularly dependent upon glutamine to fuel oxidative mitochondrial metabolism and thus may be responsive to inhibition of GLS or respiration." (PMID 25621173, 2015). "Glutaminase (GLS) inhibitors, such as CB-839, have shown significant promise in preclinical studies by blocking the conversion of glutamine to glutamate, thereby depriving tumor cells of essential substrates for biosynthesis and energy production." (PMID 40277923, 2025). "Glutaminase (GLS) acts in conjunction with glutamate-derived α-ketoglutarate in the citric acid cycle (TCA) to support cellular energy production and biosynthesis requirements, thereby promoting tumour growth and progression." (PMID 41050056, 2025). "Curcumin extensively intervenes in amino acid metabolism by inhibiting the activity of glutaminase (GLS), ornithine decarboxylase (ODC), and other enzymes, thereby disrupting polyamine homeostasis and amino acid balance, which affects tumor proliferation and antioxidant defense." (PMID 41515171, 2025). "Glutaminase (GLS) inhibitors, such as CB-839, have demonstrated significant anti-tumor effects in preclinical models by inhibiting glutamine metabolism and disrupting the carbon and nitrogen supply essential for tumor cell survival." (PMID 40255400, 2025). "Glutaminase (GLS1) inhibition reduces GSH levels, sensitizing tumor cells to ferroptosis." (PMID 40650229, 2025). "In addition, tumor cells upregulate glutamine transporters, such as solute carrier family 1 member 5 (SLC1A5) and glutaminase (GLS), to enhance glutamine uptake and utilization." (PMID 40223597, 2025). "GLS is considered prooncogenic and overexpressed in many tumours, while GLS2 may act as prooncogenic or as a tumour suppressor." (PMID 39796278, 2025). "This suggests pre‐chemotherapy metabolic priming could sensitise MS_2 tumours: preclinical studies demonstrate that inhibiting glycolytic enzymes (e.g., HK2) or glutaminase restores NADPH pools and enhances doxorubicin response." (PMID 40457119, 2025). "Additionally, the isozymes glutaminase 1 (GLS1) and GLS2 have opposing roles in tumors: GLS1 exhibits oncogenic properties, whereas GLS2 functions as a tumor suppressor." (PMID 40723225, 2025). "Reducing GCPII expression through genetic alterations or pharmacological inhibition of glutamate carboxypeptidase II (GCPII) leads to reductions in glutamate concentration and tumor growth, which are enhanced by targeting GCPII in combination with glutaminase inhibition." (PMID 38581001, 2024). "In addition, GLS expression was higher in the TAM cluster within the tumor fraction, suggesting a predominant glutamine metabolism activity in these tumor-infiltrating myeloid cells." (PMID 38701369, 2024). "By inhibiting key enzymes such as glutaminase (GLS), not only is tumor cell biosynthesis blocked, but T cell function may also be enhanced, offering a new perspective for tumor immunotherapy." (PMID 39654883, 2024). "Additionally, we also investigated the expression of cuproptosis‐related genes between tumour and normal samples in the TCGA ESCA cohort and found that the expression of DLAT, GLS and LIPT1 was increased in tumour samples (p < 0.05)." (PMID 38429907, 2024). "This activation leads to metabolic reprogramming and increased activity of enzymes like glutaminase (GLS), indoleamine 2,3-dioxygenase (IDO), and arginase 1 (ARG1), depleting essential amino acids in the tumor microenvironment that are vital for effector immune cell function." (PMID 39664377, 2024).
tumor (continued). "Besides, it is found that GLS antagonists, such as CB-839, can increase the content of Gln in TME by inhibiting the utilization of Gln by tumor cells." (PMID 38264667, 2023). "Conversely, employing a non-tumor cell specific glutaminase inhibitor does not yield the same efficacious results." (PMID 37842241, 2023). "We found that five cuprotosis molecules, DLAT, PDHA1, FDX1, GLS and CDKN2A, were significantly different between paired tumour and adjacent non-tumour samples from the TCGA-STAD cohort, and LIAS, DLD, DLAT and MTF1 were significantly different among the four pathologic T categories 1–4." (PMID 36895378, 2023). "However, glutaminase inhibition also impairs CD8+ T cell activation and anti-tumour capabilities in the TME23." (PMID 37407815, 2023). "For example, glutaminase inhibitor CB-893, glutamine metabolism inhibitor JHU083, and arginase 1 inhibitor INCB001158 can not only inhibit tumor progression but also increase the immune system in TME cell infiltration." (PMID 36992704, 2023). "Numerous attempts have been made to target GLS and ASCT2 in MM to reduce tumor burden." (PMID 36902326, 2023). "However, tumor-specific inhibition of glutamine uptake and glutaminase activity in combination with anti-PD-L1 therapy strongly induced CD8+ T cell proliferation and granzyme B production, while abating tumor growth." (PMID 37842241, 2023). "Tumor-bearing mice were imaged with [18F]FSPG PET before and one week following the initiation of treatment with either EGFR-targeted monoclonal antibody (mAb) therapy, glutaminase inhibitor therapy, or the combination." (PMID 36961000, 2023). "For example, the addition of the clinically well-tolerated glutaminase inhibitor, CB839 (to preempt GDH ETC electron flow), to a CPI-613 cocktail may prove effective in some cases or tumor types." (PMID 35675354, 2022). "Glutaminase (GLS) is a mitochondrial enzyme that starts this process by converting GLU to glutamate, which is then used in a number of activities that help tumor cells grow and survive, including energy production, amino acid synthesis, and glutathione formation." (PMID 35956989, 2022). "MYC specifically activates the expression of glutamine transporter and glutaminase in tumors, thereby regulating the reprogramming of glutamine metabolism in tumors.At the same time, MYC also regulates the expression of PD-L1 and CD47 in the tumor cells." (PMID 35897036, 2022). "It is worth noting that transformation of glutamine to glutamate, catalyzed by glutaminase, is not directly recapitulated by [18F]FGln retention because once [18F]FGln is transported inside the tumor cell by ASCT2, it does not enter the glutaminolysis pathway." (PMID 35732988, 2022). "Infusions with [amide-15N]glutamine revealed persistent amidotransferase activity during glutaminase inhibition, and blocking these activities with the amidotransferase inhibitor JHU-083 also reduced tumor growth in both immunocompromised and immunocompetent mice." (PMID 36525494, 2022). "Additionally, increased mRNA level of CDKN2A, DLAT, GLS, LIPT1, and MTF1 in tumor were observed compared to normal group." (PMID 36703728, 2022). "Expressions of four transcripts including L-type amino acid transporter 1 (SLC7A5), the high-affinity L-glutamine transporter (SLC1A5), glutaminase (GLS), and glutamate dehydrogenase 1 (GLUD1) were all significantly up regulated in T3 as compared with T1 and T2 tumours." (PMID 36615660, 2022). "Inhibiting glutaminase not only reduces glutamine consumption within tumor cells but also supports MYC without inhibiting the effector function in NK cells." (PMID 35062950, 2022). "In addition, circ-PITX1 expression is upregulated in NSCLC, and its silencing inhibits GLS expression through the miR-1248-CCND2 pathway, thereby inhibiting Gln metabolism in NSCLC cells, promoting NSCLC cell apoptosis and suppressing tumor growth in vivo." (PMID 35223460, 2021).
tumor (continued). "Therefore, we knocked down ATF4 (siATF4) in renal CAKI1 tumor cells and compared the expression of SLC7A11, GCLM, and GLS after 1 and 24 h of hLcn-2 stimulation to scRNA-treated cells." (PMID 34069743, 2021). "We hypothesized that targeting of both glutamine and glucose utilization pathways via dual inhibition of GLS and tyrosine kinase signalling pathways would lead to synergistic suppression of RCC tumor cell proliferation." (PMID 34731180, 2021). "In order to verify whether SLC7A11, GCLM, and GLS are specifically induced by iron-loaded Lcn-2, we stimulated CAKI1 tumor cells with iron-free, apo-Lcn-2 (aLcn-2) and a mutant form (mLcn-2) deficient of its iron binding capacity compared to hLcn-2." (PMID 34069743, 2021). "Indeed, the combination of the glutaminase 1 (GLS1) inhibitor with PD1 and PD-L1 antibodies enhanced anti-tumor effectiveness by overcoming a metabolic checkpoint blocking T cell activation in CRC." (PMID 34200820, 2021). "Here we analyze the effect of GLS inhibition on stem cell-enriched GBM in vitro models (GBM stem-like cells; GSCs), which have been suggested to be responsible for the emergence of therapy resistance and tumor relapse." (PMID 32337072, 2020). "Notably, STSs expressing high GLS exhibit increased dependency on glutamine, required to support the TCA cycle, aspartate production, and subsequently, nucleotide synthesis for tumour cell growth." (PMID 31980651, 2020). "Furthermore, combined GLS and mTOR inhibition resulted in massive GBM cell death and tumor growth inhibition in a xenograft model, underscoring the importance of compensatory glutamine metabolism in promoting GBM resistance to mTOR inhibitor treatment." (PMID 32013066, 2020). "In order to better understand mechanisms responsible for response and resistance to glutaminase inhibitors, we studied glutamine utilization in the two xenografts by infusion of 13C-enriched glutamine and ex vivo 13C NMR tumor analysis, combined with gene- and protein expression data." (PMID 31088535, 2019). "In this regard, the importance of glutamine-derived nitrogen for tumor growth in vivo has not been evaluated, partly because most of these reactions do not rely on glutaminase activity." (PMID 31212591, 2019). "In addition, the expression of glutaminase genes GLS and GLS2 correlates with increased tumor growth rates." (PMID 31801490, 2019). "Conversely, a large glutamine pool size was observed in estrogen receptor–positive tumor extracts with low glutamine use, without a change in pool size after glutaminase inhibition." (PMID 30042161, 2018). "Interestingly, multiple proteins linked to known cancer-associated metabolic pathways, such as glycolysis, serine synthesis (PHGDH), glutamine consumption (GLS), were lower in the ERPR tumours." (PMID 26725330, 2016). "Similar results were observed in both PIK3CA‐WT and mutant human CRC cell lines with enhanced HLA‐A,B,C levels on the cell surface after knockdown of GLS or treatment with CB‐839, suggesting that GLS inhibition‐induced tumor antigen presentation is independent of PIK3CA status." (PMID 39482885, 2025). "Although current evidence highlights hyperactivation of glutaminolysis and upregulation of GLS in HNSCC, it remains unclear whether these metabolic alterations are simply consequences of the tumor state or whether they directly contribute to tumor initiation and progression." (PMID 41439982, 2025). "EGFR activates mTORC1 via the PI3K/AKT pathway, upregulating glutaminase (GLS) to fuel nucleotide synthesis, while STAT3-mediated cell cycle progression creates a self-reinforcing loop that provides both biosynthetic precursors and proliferative signals for rapid tumor growth." (PMID 40904507, 2025).
tumor (continued). "To date, targeting glutamine metabolism enzymes, such as glutaminase (GLS1, an enzyme that restricts the conversion of glutamine to glutamate and its cataplerotic entry into the TCA cycle), in combination with chemotherapy is promising for suppressing tumor growth." (PMID 38879686, 2024). "Metabolic reprogramming of tumor cells in the TME promotes the expression of L-glutamine transporters ASCT2(SLC1A5) and SN2(SLC38A5), alongside glutamic acid–metabolizing enzymes (e.g., glutaminase [GLS]), glutamine synthetase, and aminotransferases, thereby increasing L-glutamine intake." (PMID 39227970, 2024). "ERK5 may function as a mechanism to finely tune GLS levels in tumor cells to assure that the glycolysis pathway is not obliterated by an extremely enhanced glutaminolysis rate." (PMID 38542254, 2024). "Moreover, further analysis was made to investigate the mRNA expression level of CRGs between normal and CRC samples, and we found that the expressions of FDX1, DLD, DLAT, PDHB, and MTF1 were significantly decreased, whereas LIPT1, GLS, and CDKN2A were significantly upregulated in tumor samples." (PMID 37006250, 2023). "Moreover, tumours with greater elevations in glutaminase activity significantly correlated with decreased GCN5L1 protein levels but not with GLS1 or GLS2 protein levels." (PMID 35538890, 2022). "Therefore, in the future, additional studies will be required to unambiguously show if glutaminase co-activity is truly required for a long-term antileukemic response in ASNS-negative tumor cells or not." (PMID 35205650, 2022). "In the Human Protein Atlas database, the expressions of GLS, MTF1 and PDHA1 in tumor tissues were lower compared with those in normal tissues, while the expressions of DLAT and PDHB were significantly higher in tumor tissues compared with those in normal tissues." (PMID 36620594, 2022). "With the catalysis of glutaminase (GLS), glutamine (GLN) can be converted into glutamate (GLU), which is then converted into α-ketoglutarate (α-KG) by glutamate dehydrogenase (GDH) to participate in the tricarboxylic acid cycle (TCA cycle) and provide energy for tumor growth." (PMID 33397440, 2021). "Furthermore, the expression distribution characteristics of ASCT2, GLS, and Ki‐67 were consistent in most of the OSCC cases, as demonstrated by the fact that all three biomarkers were highly expressed in the marginal bud region of the tumor." (PMID 32162845, 2020). "Our work highlights the potential for both systemic- and paracrine tumour-derived pyruvate to limit the antitumour activity of glutaminase inhibitors and uncovers a possible rational combination that includes addition of MCT1 inhibitor to glutaminase inhibitor therapy." (PMID 32450839, 2020). "Moreover, subcutaneous and orthotopic lung implants of Nf1‐mutant LUAD cells in nude mice exhibited decreased tumor growth when mice were administered CB‐839 or AOA, supporting glutaminase and/or Psat1 inhibition as a possible treatment strategy in Nf1‐mutant LUAD tumors." (PMID 31036704, 2019). "As a consequence, inhibition of glutaminolysis in vivo (using the GLS inhibitor CB-839, currently under clinical investigation in the treatment of hematologic malignancies and solid cancers including lung cancers) does not affect tumor cell progression." (PMID 30564554, 2018). "Within the tumor cells, lactate obtained from the neighboring tumor stroma stabilizes the HIF2α which in turn activates the oncogene c-Myc and upregulates the expression of both glutamine transporter ASCT2 and glutaminase 1 (GLS1)—thus ensuring a steady flux of glutamine in the cells." (PMID 28447025, 2017). "Notably, the off-target glutaminase (GLS) activity of asparaginase is not required for its anti-tumour effects." (PMID 27126896, 2016).